ARHGEF3 (Rho guanine nucleotide exchange factor 3)
Description:
Acts as a guanine nucleotide exchange factor (GEF) for RhoA and RhoB GTPases.
Synonyms: XPLN; STA3; GEF3; DKFZP434F2429
Tractability: PROTAC: ubiquitination databases record sites on it.
Gene: Protein-coding gene on chromosome 3 (56,727,418 to 57,079,329, reverse strand). Ensembl gene ENSG00000163947.
Subcellular location: Cytoplasm
Subcellular location (Human Protein Atlas): Cytosol
Pathways (Reactome):
Signal Transduction: G alpha (12/13) signalling events; NRAGE signals death through JNK; RHOA GTPase cycle; RHOB GTPase cycle
Gene Ontology:
Molecular function: protein binding; guanyl-nucleotide exchange factor activity
Biological process: positive regulation of Rho protein signal transduction; regulation of small GTPase mediated signal transduction; Rho protein signal transduction; intracellular signal transduction
Cellular component: cytosol; cytoplasm
Genetic constraint (gnomAD): Loss-of-function variants: 27 observed, 63 expected, observed/expected ratio (o/e) 0.43, 90% interval 0.31 to 0.59. The upper end of that interval is the gene's LOEUF score, 0.59, which puts it in group 2 of 6, group 1 being the genes least tolerant of losing a copy. Missense variants: 526 observed, 666.51 expected, observed/expected ratio (o/e) 0.79, 90% interval 0.73 to 0.85. Synonymous variants: 262 observed, 257.46 expected, observed/expected ratio (o/e) 1.02, 90% interval 0.92 to 1.13.
Homologues: Orthologues: pig ARHGEF3 (98% identical), chimpanzee ARHGEF3 (95% identical), macaque ARHGEF3 (95% identical), dog ARHGEF3 (93% identical), rabbit ARHGEF3 (93% identical), mouse Arhgef3 (92% identical), guinea pig ARHGEF3 (91% identical), rat Arhgef3 (89% identical), tropical clawed frog arhgef3.2 (78% identical), zebrafish arhgef3 (70% identical), Caenorhabditis elegans prhg-1 (16% identical), Drosophila melanogaster cyst (15% identical). Paralogues in human: NET1 (54% identical), ARHGEF12 (21% identical), ARHGEF11 (20% identical), ARHGEF28 (19% identical), ARHGEF1 (19% identical), ARHGEF2 (18% identical), ARHGEF18 (17% identical), PLEKHG6 (14% identical).
Diseases named in the same sentence as ARHGEF3 in open-access papers:
ARHGEF3 is named in the same sentence as 32 diseases in open-access papers, as found by Europe PMC text mining. Sharing a sentence is not in itself a finding about the gene and the disease. The quoted sentences say what the papers report.
nasopharyngeal carcinoma (9 papers, 2016 to 2023). A carcinoma arising from the nasopharyngeal epithelium. "While most of the variants flagged in the polygenic model are novel, the gene ARHGEF3 has been implicated in promoting nasopharyngeal carcinoma in Asians34." (PMID 33976257, 2021). "Human Arhgef3 has been linked with osteoporosis and has oncogenic correlation with nasopharyngeal carcinoma (NPC), where a gain of function results in NPC tumorigenesis and metastasis and loss of function dramatically induces apoptosis in cancer cells." (PMID 35011606, 2021). "In contrast, elevated ARHGEF3 expression is a crucial contributor to the pathogenesis of nasopharyngeal carcinoma (NPC) by inhibiting cell apoptosis and potentially used as a novel marker for prognosis and an effective target for treatment." (PMID 37315301, 2023). "In nasopharyngeal carcinoma cells, ARHGEF3 inhibits apoptosis by regulating the expression of ILP-2, which in turn inhibits the activation of caspases-3." (PMID 35814477, 2022). "By contrast, there are few reports on ARHGEF3 and HSPA13 in chickens, most of the articles about the ARHGEF3 are related to disease in human, such as acute myeloid leukemias, nasopharyngeal carcinoma cell pathogenesis and platelet function, as for HSPA13, few studies in NCBI database." (PMID 31744899, 2020). "ARHGEF3 encodes Rho-guanine nucleotide exchange factor (GEF) 3, whose expression level is positively associated with metastasis and more advanced clinical stages of nasopharyngeal carcinoma." (PMID 30338036, 2018). "A recent study showed that knockdown of ARHGEF3 markedly inhibits NPC (nasopharyngeal carcinoma) cell growth and migration." (PMID 32139661, 2020). "Thus, it is clear that the increased expression of ARHGEF3 prevents apoptosis through the upregulation of ILP-2 (P<0.01), which plays a key oncogenic role in the pathogenesis of nasopharyngeal carcinoma." (PMID 35814477, 2022).
osteoporosis (4 papers, 2021 to 2025). A condition of reduced bone mass, with decreased cortical thickness and a decrease in the number and size of the trabeculae of cancellous bone (but normal chemical composition), resulting in increased fracture incidence. "ARHGEF3-related diseases include methotrexate-related lymphoproliferation and osteoporosis." (PMID 34350290, 2021). "This study identifies ARHGEF3 and RHHOA as potential regulators genes that act in bone metabolism and can be used as targets in specific therapies for osteoporosis." (PMID 37675799, 2023).
lung cancer (3 papers, 2022 to 2025). A malignant neoplasm involving the lung. "ARHGEF3 enhances ACLY protein stability by reducing acetylation at Lys17 and Lys86 of ACLY, leading to the dissociation of ACLY from its E3 ligase, NEDD4, making it a promising therapeutic target in non‐small cell lung cancer." (PMID 39778006, 2025). "ARHGEF3, a member of the Rho GEF family, is highly expressed in non‐small cell lung cancer." (PMID 39778006, 2025). "However, the function of ARHGEF3 in lung cancer has not been reported, and the effects of ARHGEF3 on cancer metabolism remain unclear." (PMID 36241648, 2022).
acute myeloid leukemia (2 papers, 2016 to 2020). Acute myeloid leukemia (AML) is a group of neoplasms arising from precursor cells committed to the myeloid cell-line differentiation. "It has been reported that ARHGEF3, a Rho-guanine nucleotide exchange factor (GEF) upregulated in acute myeloid leukemia (AML), modulates AML differentiation through activation of RhoA and pathways directly controlled by small GTPase family proteins." (PMID 27028992, 2016).
hepatocellular carcinoma (2 papers, 2022). A malignant tumor that arises from hepatocytes. "Given the observed inhibition of HCV replication by ARHGEF3 following infection of Huh7 human hepatoma cells, we wanted to determine whether the gene was expressed in chronically HCV-infected liver in vivo where it could also contribute to controlling viral replication." (PMID 36016278, 2022).
Hirschsprung disease (2 papers, 2020 to 2021). Hirschsprung disease (HSCR) is a congenital intestinal motility disorder that is characterized by signs of intestinal obstruction due to the presence of an aganglionic segment of variable extent in the terminal part of the colon. "Humans with mutations in the RET locus have Hirschsprung disease, and ARHGEF3 is located at the RET-dependent susceptibility locus identified at 3p21." (PMID 35174167, 2021). "Moreover, studies on genetic variation in ARHGEF3 and genome-wide association studies have predicted exciting novel roles of ARHGEF3 in controlling bone mineral density, platelet formation and differentiation, and Hirschsprung disease." (PMID 35174167, 2021). "Taken together, our present data show that genetic variants and haplotypes in RET, ARHGEF3 and CTNNAL1 confer an altered risk to Hirschsprung disease in the Han Chinese population." (PMID 32139661, 2020). "Our current work presented strong associations of ARHGEF3 and CTNNAL1 with Hirschsprung disease." (PMID 32139661, 2020). "Furthermore, studies on ARHGEF3 genetic variation and genome-wide association studies (GWASs) have identified interesting new roles of ARHGEF3 in modulating bone mineral density (BMD), platelet formation and differentiation, and Hirschsprung disease." (PMID 35174167, 2021).
idiopathic pulmonary fibrosis (2 papers, 2021 to 2023). Idiopathic pulmonary fibrosis (IPF) is a nonneoplastic pulmonary disease that is characterized by the formation of scar tissue within the lungs in the absence of any known cause. "A study has shown that ARHGEF3 plays a regulatory role in pulmonary fibrosis through mTORC2." (PMID 36600215, 2023).
osteosarcoma (2 papers, 2021 to 2023). A usually aggressive malignant bone-forming mesenchymal neoplasm, predominantly affecting adolescents and young adults. "By using the KM Plotter software, miRNA-124 and ARHGEF3 were obviously associated with the overall survival of patients with osteosarcoma." (PMID 34350290, 2021). "ARHGEF3 downregulation may be associated with invasion, metastasis, and proliferation in osteosarcoma because this gene specifically activates RHOA and RHOB, which play a role in bone cell biology." (PMID 37315301, 2023). "Although the difference in the expression of other cell lines was not as significant as that of 143B cells, this result can prove to some extent that the high expression of ARHGEF3 in osteosarcoma cell lines may be associated with poor prognosis of osteosarcoma cells." (PMID 34350290, 2021). "To further assess the expression of ARHGEF3, we selected four osteosarcoma cell lines to detect its mRNA level and protein expression, and the control group was the normal osteoblast hFOB1.19." (PMID 34350290, 2021). "Consistent with the microarray data, ARHGEF3 was highly expressed in hFOB1.19 cells and was low expressed in various osteosarcoma cell lines at both mRNA and protein levels." (PMID 34350290, 2021). "The WB and qRT-PCR results revealed that the expression level of ARHGEF3 in osteosarcoma (MG63, 143B, U2OS, and U2R) was indeed much lower than that in human osteoblasts (hFOB1.19), especially in the 143B cell line." (PMID 34350290, 2021). "Furthermore, ARHGEF3 was found downregulated in osteosarcoma cells by performing qRT-PCR and WB experiments." (PMID 34350290, 2021). "The outcome indicated that the expression level of ARHGEF3 and PLD5 may have an obvious association with the overall survival of patients with osteosarcoma." (PMID 34350290, 2021). "Survival analysis also indicated that hsa-mir-124 and target mRNAs (ARHGEF3 and PLD5) may have an obvious association with the prognosis of patients with osteosarcoma." (PMID 34350290, 2021). "ARHGEF3 may act as a therapeutic and prognostic target of osteosarcoma." (PMID 34350290, 2021). "Therefore, to know whether ARHGEF3 has the same performance in osteosarcoma, we conducted migration, invasion, and wound healing assays." (PMID 34350290, 2021).
prostate carcinoma (2 papers, 2018 to 2024). A carcinoma that arises from epithelial cells of the prostate gland. "Previous research identified a novel genomic fusion event between NDUFAF6 and ARHGEF3 in prostate cancer." (PMID 38459583, 2024).
B-cell lymphoma (1 paper, 2021). "ARHGEF3 contains the diffuse B-cell lymphoma homology and pleckstrin homology domains but lacks similarity with other known functional domains." (PMID 35174167, 2021).
endometrial cancer (1 paper, 2023). Primary or metastatic malignant neoplasm involving the endometrium (mucous membrane that lines the endometrial cavity). "According to the Human Protein Atlas database, high ARHGEF3 expression is favorable for patient survival and potentially a prognostic marker for renal cancer, endometrial cancer, and head and neck cancer, and others." (PMID 37315301, 2023).
glioma (1 paper, 2019). A benign or malignant brain and spinal cord tumor that arises from glial cells (astrocytes, oligodendrocytes, ependymal cells). "According to recent publications, mediating RhoA associated biological processes, ARHGEF3 has been confirmed to interact with IDH and has unique methylation status in glioma." (PMID 31803734, 2019). "As for its specific role for glioma subtyping, similar with gene ARHGEF3, such microRNA participates in TGF-beta signaling pathway and has been validated to have different methylation status together with expression pattern in different IDH expression glioma subtypes." (PMID 31803734, 2019). "The next probe cg20138711 targeting ARHGEF3 was screened out in our study, which were deemed to contribute to IDH-dependent glioma subtyping." (PMID 31803734, 2019).
hypochromic anemia (1 paper, 2021). Anemia caused by the reduction of hemoglobin in relation to the red cell volume. "When the translation of ARHGEF3 was blocked with MO antisense oligonucleotides at an early stage, the ARHGEF3 MO-injected embryos showed normal morphologic development but evident defects in hematopoiesis, especially with microcytic and hypochromic anemia." (PMID 35174167, 2021).
non-small cell lung carcinoma (1 paper, 2022). A group of at least three distinct histological types of lung cancer, including non-small cell squamous cell carcinoma, adenocarcinoma, and large cell carcinoma. "In this study, we found that ARHGEF3 was a new regulator of ACLY in non-small cell lung cancer, which stabilized ACLY by reducing its acetylation and decreasing its ubiquitination, thus promoting tumor growth and progression." (PMID 36241648, 2022). "Herein, we demonstrated that ARHGEF3, a member of the Rho GEFs family, played an important role in non-small cell lung cancer (NSCLC)." (PMID 36241648, 2022). "Taken together, our findings uncover a novel function of ARHGEF3, suggesting that ARHGEF3 is a promising therapeutic target in non-small cell lung cancer." (PMID 36241648, 2022). "We found that ARHGEF3 was highly expressed in non-small cell lung cancer and facilitated cancer cell proliferation of NSCLC cells in vitro and in vivo." (PMID 36241648, 2022). "In conclusion, ARHGEF3 is a new potential therapeutic target for non-small cell lung cancer." (PMID 36241648, 2022). "In conclusion, our studies unravel a novel function of ARHGEF3 independent of GEF activity in non-small cell lung cancer." (PMID 36241648, 2022).
psoriasis (1 paper, 2017). An autoimmune condition characterized by red, well-delineated plaques with silvery scales that are usually on the extensor surfaces and scalp. "The four genetic variants—rs1802073 G>T in SFRP4, rs1105223T>C in CRB2, rs3821414T>C in ARHGEF3, rs11086065A>G in ANKLE1—could be validated as predictive markers for the response to acitretin in psoriasis." (PMID 28146080, 2017).
tumor (11 papers, 2016 to 2026). "Furthermore, to detect whether overexpression of ACLY could rescue the loss of tumor formation in ARHGEF3-deficient cells, A549 stable cell lines with ARHGEF3 knockdown combined with ACLY overexpression were constructed." (PMID 36241648, 2022). "Here, we demonstrated that tumor-intrinsic ARHGEF3 reprogrammed the tumor microenvironment into a T-cell-inflamed state, resulting in potent antitumor effects." (PMID 42023986, 2026). "The result demonstrated that the expression of Ki67 was decreased in ARHGEF3-knockdown tumors, indicating that ARHGEF3 knockdown inhibited cell proliferation and tumor growth in vivo." (PMID 36241648, 2022). "Our analyses also found that high ARHGEF3 expression in our NPC cohorts was positively correlated with tumor T status, distant metastasis, and advanced clinical stage, suggesting that high expression of ARHGEF3 facilitates a malignant phenotype in NPC." (PMID 27028992, 2016). "The results revealed that ARHGEF3 knockdown attenuated tumor growth and obviously reduced tumor weight and volume, but ACLY overexpression could alleviate the tumor-inhibiting effects of ARHGEF3 knockdown." (PMID 36241648, 2022). "Moreover, we established a xenograft model to investigate the effect of ARHGEF3 on tumor growth in vivo." (PMID 36241648, 2022). "We did not detect tumor nodule formation in the livers of all mice examined, but overexpression of ARHGEF3 significantly increased metastasis in lung (P<0.01)." (PMID 27028992, 2016). "The results demonstrated that knockdown of ARHGEF3 led to slower tumor growth and significantly reduced tumor volume and tumor weight, and the cells with ARHGEF3 knockdown even could not form obvious xenografts in some models." (PMID 36241648, 2022).
cancer (9 papers, 2014 to 2025). A tumor composed of atypical neoplastic, often pleomorphic cells that invade other tissues. "Moreover, in a tail vein injection mouse model of cancer metastasis ectopic overexpression of ARHGEF3 in HONE1 cells led to a significant increase in the number of metastatic lung lesions." (PMID 27028992, 2016). "The expression of ARHGEF3 in 8 NSCLC patients was also examined and showed that ARHGEF3 expressed at a higher level in most cancer tissues than in adjacent normal tissues." (PMID 36241648, 2022). "siRNA was used to specifically interfere with ARHGEF3 expression in H1299 and A549 cells, and the cell growth assays revealed that ectopic ACLY expression recovered cancer cell proliferation." (PMID 36241648, 2022). "However, the role of ARHGEF3 in NSCLC has not been reported, and the function of ARHGEF3 in cancer remains to be further elucidated." (PMID 36241648, 2022). "However, the potential roles and biological mechanisms of the GEF family gene ARHGEF3 in human cancers have not been studied." (PMID 27028992, 2016).
infection (2 papers, 2022 to 2025). The state of being infected such as from the introduction of a foreign agent such as serum, vaccine, antigenic substance or organism. "Our study highlights the previously underexplored role of ARHGEF3 in macrophages during infection, indicating its potential as a target for anti-infection drug development." (PMID 40721684, 2025). "One question resulting from our studies is whether this inhibition could be influenced by ARHGEF3/XPLN in the liver in natural infection." (PMID 36016278, 2022). "Thus, ARHGEF3 expression could be detected in the liver or liver-derived cells where it may be very modestly induced during infection or IFN stimulation compared with other anti-HCV ISG factors." (PMID 36016278, 2022). "In HCV-infected liver biopsies, ARHGEF3 was modestly upregulated 1.5–2-fold during HCV gt1 and gt3 infection; by comparison, IFI27 and RSAD2/VIPERIN were induced >10–100 fold during HCV infection." (PMID 36016278, 2022). "However, no activators targeting ARHGEF3 have been identified by far, developing of which targeting macrophages to increase infection resistance possesses a potential clinical implication." (PMID 40721684, 2025).
ARHGEF3 also shares sentences with these, for which no sentence is quoted: breast carcinoma (2 papers); Autosomal dominant hyper-IgE syndrome (1); bacterial infection (1); colorectal cancer (1); COVID-19 (1); gastric cancer (1); glioblastoma (1); head and neck cancer (1); Listeria monocytogenes infection (1); Moyamoya disease (1); oral carcinoma (1); postmenopausal osteoporosis (1); renal carcinoma (1); thyroid diseases (1).